BDNF (brain derived neurotrophic factor)
Diseases named in the same sentence as BDNF in open-access papers (continued):
Sharing a sentence is not in itself a finding about the gene and the disease.
schizophrenia (continued). "We found weak MR evidence for a small protective effect of BDNF on schizophrenia and bipolar disorder in analyses of cis variants only, consistent with previous meta-analyses." (PMID 34280516, 2021). "In this what we believe to be the first report of in vivo relationship between miR-195 and BDNF in schizophrenia, higher miR-195 expression was significantly associated with lower BDNF protein expression in schizophrenia." (PMID 33558459, 2021). "This was supported by another study, showing that decreased BDNF serum levels were associated with weight gain in female schizophrenia patients receiving long-term antipsychotic treatment." (PMID 35047549, 2021). "These novel findings strongly suggest that decreased BDNF levels are associated with several behavioral endophenotypes of schizophrenia." (PMID 33888685, 2021). "In summary, we showed that BDNF haploinsufficiency in mature adult mice is associated with different behavioral endophenotypes of schizophrenia and that these endophenotypes are rescued by EE housing." (PMID 33888685, 2021). "First, our results indicate some evidence in support of a potential causal relationship between IL-6, IL-9, MCP-1, sIL-2Rα, and BDNF with schizophrenia, although only the association with IL-6 survived correction for multiple testing." (PMID 34280516, 2021). "It is interesting also to postulate that TH antioxidant, and anti-inflammatory properties together with its effects on BDNF probably also played some roles, probably linked to cholinergic abnormalities in schizophrenia." (PMID 32426546, 2020). "One study found that schizophrenia-associated rs4702 G allele-specific down-regulation of Furin by miR-338-3p reduces mature BDNF production, which affected neurodevelopmental disorder." (PMID 32392183, 2020). "Significantly downregulated BDNF expression is associated with symptoms in schizophrenia, including cognitive disorders." (PMID 32793005, 2020). "Brain derived neurotrophic factor (BDNF) has been implicated in the pathophysiology of schizophrenia." (PMID 32153434, 2020). "BDNF overexpression in neural stem cells promotes neuronal survival and functional recovery in an animal model of traumatic brain injury and BDNF is linked to diverse neurological disorders, such as mood disorders, schizophrenia, and drug-induced brain injury." (PMID 32570881, 2020). "Our findings suggest that changes in BDNF serum levels in schizophrenia are mainly associated with pathologies in axons, dendrites, and/or myelination." (PMID 32153434, 2020). "Regarding schizophrenia risk, the 66Met allele decreases BDNF release probability, producing lower efficiency in neurotrophic activity, which is required for neurogenesis and neuroplasticity." (PMID 32719625, 2020). "Our haplotype analysis showed the sex differences in the risk of developing schizophrenia for the polymorphisms of the TrkB and BDNF genes." (PMID 32351633, 2020). "Reduced BDNF levels have been observed both in post-mortem hippocampal samples, and in the plasma of drug-naïve patients with schizophrenia, while low baseline BDNF levels are associated with worse response to antipsychotic treatment." (PMID 32226399, 2020). "BDNF has also been implicated in a number of psychiatric disorders, including schizophrenia, and the development of mood disorders such as MDD and its treatment." (PMID 30995790, 2019). "Our result contradicts previous studies on chronic schizophrenia patients and a recent meta-analysis, which suggested that higher BDNF expression was associated with better neurocognitive performance in schizophrenia patients." (PMID 31420036, 2019). "Individuals with schizophrenia are characterized by low circulating levels of BDNF, and there is a positive association between levels of BDNF and reasoning/problem solving in schizophrenia." (PMID 31708824, 2019).
schizophrenia (continued). "A variant of BDNF Val66Met polymorphism was shown to moderate the impact of childhood adversity on later expression of affective symptoms in schizophrenia patients." (PMID 30983960, 2019). "Considering the observations that cortical GABAergic interneurons in schizophrenia are disrupted, low BDNF level is likely to be associated with fewer inhibitory neurotransmissions in schizophrenia." (PMID 31261897, 2019). "In past studies, methylation levels of BDNF exon I and IV promoters in peripheral blood were studied more extensively, and were found be to be associated with severe mental disorders, such as schizophrenia, bipolar mania and MDD." (PMID 31027379, 2019). "Most studies have been carried out in chronic schizophrenia patients, but recent papers have described reduced peripheral BDNF levels in high clinical risk groups and patients with the first episode of schizophrenia." (PMID 31098654, 2019). "Many previous reports using small sample sizes (at least a few dozen) have demonstrated a positive correlation between peripheral BDNF levels and cognition as follows: higher levels of BDNF are associated with better cognitive functioning in schizophrenia." (PMID 29896133, 2018). "A case-control meta-analysis showed a significant association between BDNF rs6265 and schizophrenia." (PMID 30233327, 2018). "The BDNF GT repeat polymorphism is associated with age at onset, therapeutic response, susceptibility, and chlorpromazine-induced extrapyramidal syndrome in schizophrenia." (PMID 29867348, 2018). "Altogether, BDNF is closely associated with symptomatology and cognitive dysfunction in schizophrenia." (PMID 29896133, 2018). "In terms of genetic-structural MRI studies, “patients with schizophrenia are found to have reductions in the frontal, temporal, parietal cortices, and limbic regions, which are associated with BDNF, COMT, and neuregulin-1 (NRG1) genes”." (PMID 30349492, 2018). "Brain-derived neurotrophic factor (BDNF) is the most widely distributed neurotrophic factor in the brain, the levels of which have been associated with schizophrenia." (PMID 28272307, 2017). "A longitudinal study using imaging measures found that serum BDNF levels were associated with hippocampal volume alterations in schizophrenia patients." (PMID 35098038, 2017). "In contrast to neuroendocrine and immune markers that were associated with treatment response, BDNF was confirmed to be significantly reduced in plasma samples of schizophrenia patients, either in medicated or in drug-naïve patients." (PMID 28358316, 2017). "Carriers of the Val66Met polymorphism of BDNF reported decreased BDNF plasma levels in schizophrenia-affected individuals compared to healthy subjects." (PMID 35098038, 2017). "Some studies have shown that the BDNF Met allele or the Met/Met genotype is associated with the increased risk of developing schizophrenia." (PMID 28358316, 2017). "It is known or predicted to regulate hundreds of genes, whose targets include many schizophrenia susceptibility genes, such as BDNF, ZNF804A, TCF4 and CACNA1C37,38." (PMID 29118371, 2017). "The association studies between genetic polymorphisms of BDNF and schizophrenia resulted in contradictory findings." (PMID 28358316, 2017). "For instance, schizophrenia has been associated both with decreased self-reported Perspective Taking and with the BDNF Val66Met polymorphism." (PMID 26901829, 2016). "On the contrary, Kordi-Tamandani and colleagues revealed that the methylated allele frequency of the BDNF promoter IV was lower in the schizophrenia patients, than in controls." (PMID 27267954, 2016). "In conclusion, astrocytes react to injury or stress by increasing expression of several proteins implicated in schizophrenia, including BDNF and its receptors." (PMID 26700309, 2015). "These signaling factors are not only associated with the pathophysiology of schizophrenia, but are also involved in the regulation of BDNF signaling." (PMID 26700309, 2015).
schizophrenia (continued). "In the present study, we sought to define the relationship between peripheral BDNF levels andthe neural processes underlying probabilistic association learning in healthy people andpeople with schizophrenia." (PMID 25162472, 2015). "Recently, a proof-of-concept study reported an association of BDNF Val66Met polymorphism with cathodal tDCS induced plasticity in schizophrenia patients, warranting further research in clinical populations, especially those of the older demographic." (PMID 26097454, 2015). "We predicted that brain activity would correlate positively withperipheral BDNF levels during probabilistic association learning in healthy adults andthat this relationship would be altered in schizophrenia." (PMID 25162472, 2015). "No strong, significant correlations were obtained between plasma BDNF levels andprobabilistic association learning performance after 48 trials in controls(r = 0.19, p = 0.36) or in people with schizophrenia(r = 0.17, p = 0.53)." (PMID 25162472, 2015). "Lower levels of both brain and blood BDNF havealso been implicated in the majority of studies of the pathophysiology of schizophrenia." (PMID 25162472, 2015). "Single locus analysis showed significant association of nine variants from SLC6A3, PIP4K2A and BDNF genes with incomplete antipsychotic response in schizophrenia patients with high severity." (PMID 25025909, 2014). "Thirdly, BDNF principally exercises its influence through neuroanatomical areas known to be associated with symptom domains in schizophrenia, including the prefrontal cortex and hippocampus." (PMID 24672724, 2014). "The association of BDNF with hippocampal volume alterations in schizophrenia merits further investigation and replication in larger longitudinal studies." (PMID 24551075, 2014). "In the present longitudinal study we investigated the association between serum BDNF levels and hippocampal volumes in a sample of fourteen first-episode drug-naïve patients with schizophrenia (FEP)." (PMID 24551075, 2014). "Abnormalities in brain-derived neurotrophic factor (BDNF)/trkB signaling have been implicated in the etiology of schizophrenia and mood disorders." (PMID 24802307, 2014). "The association between BDNF gene functional Val66Met polymorphism rs6265 and the schizophrenia is far from being consistent." (PMID 24069289, 2013). "Others have shown an association between the BDNF gene single nucleotide polymorphism (SNP) val66met and schizophrenia in some populations." (PMID 23781174, 2013). "Brain-derived neurotrophic factor (BDNF) has been implicated in the pathophysiology of schizophrenia, yet its role in the development of specific symptoms is unclear." (PMID 23781174, 2013). "Our study finding of significantly deficient serum BDNF level in antipsychotic-naïve schizophrenia patients replicates previous similar reports (13, 25, –27)." (PMID 23847552, 2013). "Altered BDNF signaling has been implicated in a number of psychiatric illnesses, including schizophrenia and depression." (PMID 24155701, 2013). "Altered brain-derived neurotrophic factor (BDNF) signaling has been associated with schizophrenia through post-mortem, blood biomarker and genetic association studies." (PMID 23781174, 2013). "Apart from medication status, symptom profile of schizophrenia patients is another important factor with which BDNF level has been linked." (PMID 23847552, 2013). "BDNF has been demonstrated to interact with various neurotransmitter systems that are implicated in schizophrenia, such as dopamine, glutamate, serotonin, and GABA." (PMID 23847552, 2013). "In summary, in this study we tested for the first time the relationship between the BDNF Val66Met polymorphism and MetS in patients with schizophrenia under long-term clozapine treatment." (PMID 23967328, 2013). "Paranoid schizophrenia is the most common type of schizophrenia, and little research studied the association between specific schizophrenia subtype and polymorphism rs6265 in BDNF gene." (PMID 24069289, 2013).
schizophrenia (continued). "The neurotrophic factors best known for their association with schizophrenia are Brain-derived Neurotrophic Factor (BDNF), Nerve Growth Factor (NGF), and neurotrophin-3 (NT-3)." (PMID 22457764, 2012). "The same Val66Met genetic variant of BDNF has been largely studied as a risk factor for bipolar affective disorder, schizophrenia and other psychiatric disorders." (PMID 19844571, 2009). "There are a number of other RTK-binding molecules in addition to BDNF, which are implicated in schizophrenia." (PMID 18335055, 2008). "For example, deficits in brain derived neurotrophic factor (BDNF) signaling are implicated in many abnormalities found in schizophrenia." (PMID 18335055, 2008). "Indeed, the increase in pro-BDNF was recently demonstrated in patients at ultra-high risk of psychosis, and a higher pro-BDNF/m-BDNF ratio was shown in patients with first-episode schizophrenia." (PMID 41010622, 2025). "Altered BDNF expression has been implicated in the pathogenesis of schizophrenia." (PMID 40867540, 2025). "In the view of the available literature data and our findings, it is tempting to hypothesize that such increased apoptosis in patients with treatment-resistant schizophrenia may be linked with the pro-BDNF-FasL link." (PMID 41010622, 2025). "In the literature, a decrease in BDNF plasma levels is associated with impaired brain health, whereas high levels of BDNF are associated with an improved clinical outcome in patients with schizophrenia." (PMID 40407530, 2025). "Notably, reduced BDNF mRNA levels have been reported in rats with neonatally induced lesions of the vHPC (a neurodevelopmental model that mimics features associated with schizophrenia)." (PMID 40867109, 2025). "In addition to BDNF, several proteins that regulate BDNF trafficking have been implicated in schizophrenia." (PMID 41254423, 2025). "Notably, alterations in KIF13A and KIF13B expression, htt expression, and CAPS2, a secretory granule-associated protein implicated in BDNF-regulated exocytosis, have all been noted in patients with schizophrenia." (PMID 41254423, 2025). "Specifically, in the “schizophrenia-female” group, we observed a significantly higher incidence of the rs6265-T (V66M) variant in the BDNF gene (p = 0.0180, n = 47) and a lower occurrence of the rs1227051-A variant in the CDH23 gene (p = 0.0495, n = 47) compared to healthy volunteers." (PMID 38699454, 2024). "Studies have shown that individuals with schizophrenia often exhibit reduced BDNF levels in the brain, which could contribute to deficiencies in forming new memories, learning, and the ability to perform tasks requiring cognitive flexibility and adaptation." (PMID 38673018, 2024). "Chronic stress has been shown to reduce BDNF expression, which could worsen or precipitate cognitive dysfunction in individuals predisposed to schizophrenia." (PMID 38673018, 2024). "Reduced BDNF signaling in the cortex could be linked to alterations in the GABAergic system in schizophrenia." (PMID 39399446, 2024). "Although many anomalies associated with schizophrenia are linked to functional changes in BDNF that are critical for neuroplasticity, the regulatory mechanisms or mechanisms causing aberrant BDNF signaling in schizophrenia remain unclear." (PMID 39456824, 2024). "RIF associated with the decrease of BDNF levels in schizophrenia patients." (PMID 38362105, 2024). "In the “schizophrenia-female” group, we observed a significantly higher prevalence of the rs6265-T (V66M) variant in the BDNF gene (p = 0.0180, n = 47) and rs1944294-T (L21Stop) in the CDH2 gene (p = 0.0495, n = 47), with a decrease in the corresponding heterozygous variants." (PMID 38699454, 2024).
schizophrenia (continued). "In addition, it has also been found that the increase in 5hmC occurring in the promoter region of the BDNF gene was associated with a reduced expression of BDNF in the frontal cortex of patients with schizophrenia." (PMID 38203806, 2024). "Recent studies have also suggested that low levels of brain-derived neurotrophic factor (BDNF) may be associated with emotional regulation and memory impairments in schizophrenia." (PMID 39517317, 2024). "Importantly, patients with schizophrenia who have BDNF polymorphisms leading to inefficient BDNF expression show a more significant reduction in frontal gray matter." (PMID 39399446, 2024). "Theoretically, the high BDNF level may play a protective factor for schizophrenia and might be associated with the development and function of the motor system, especially in toddlers." (PMID 37234686, 2023). "While the green and blue clusters exhibited a correlation with the blue and green clusters, respectively, these clusters were connected to the brain's BDNF distribution related to memory function and the function of BDNF polymorphism in the pathogenesis/risk of schizophrenia." (PMID 37077958, 2023). "The current meta-analysis was conducted to verify whether ECT therapy in drug-resistant schizophrenia is associated with a change in BDNF serum levels in comparison to treatment only with antipsychotic drugs." (PMID 37685795, 2023). "Therefore, deficits in BDNF production and utilization have been implicated in the pathology of schizophrenia." (PMID 37685795, 2023). "Additionally, our research authenticates that ERVWE1 regulates the expression of brain derived neurotrophic factor (BDNF), one of schizophrenia risk gene, through glycogen synthase kinase 3β (GSK3β) phosphorylation at Ser9." (PMID 36680208, 2023). "One of the animal models displaying structural brain deficits and supports the hypothesis that BDNF is implicated in the pathophysiology of schizophrenia was obtained by administering a single injection of methylazoxymethanol acetate (MAM)." (PMID 37077958, 2023). "Therefore, the effectiveness of antipsychotic drugs used in schizophrenia treatment or electroconvulsive therapy (ECT) used in drug-resistant schizophrenia should be associated with increased BDNF concentration and the resolution of disease symptoms." (PMID 37685795, 2023). "However, the exact mechanism that would explain the potential association between thyroid hormone and BDNF levels in schizophrenia and FEP has received limited attention." (PMID 38130289, 2023). "Variations in BDNF may cause changes in the brains of schizophrenia patients, such as a reduction in frontal grey matter volume and an increase in lateral ventricles and sulcal cerebrospinal fluid volume." (PMID 37077958, 2023). "Furthermore, an association between BDNF and hippocampal volume in schizophrenia and FEP has been well documented." (PMID 38130289, 2023). "Previous findings showing that BDNF may act as a candidate marker of schizophrenia, and its serum changes have been linked with the response to treatment with antipsychotics." (PMID 37485797, 2023). "Both the decrease in BDNF and the increase in oxidative stress have been considered as common causes for neurodegenerative disorders, including cognitive dysfunction, Parkinsonism, Huntington’s disease, and schizophrenia." (PMID 36614208, 2023). "Furthermore, studies on BDNF-deficient mice and schizophrenia patients suggest a direct interplay between BDNF levels and oxidative stress in the brain." (PMID 37854466, 2023). "The abnormalities of the BDNF signal may lead to defects in brain function, thereby making individuals more susceptible to schizophrenia." (PMID 37234686, 2023). "Likewise, the existence of BDNF polymorphisms has been confirmed in DD patients with schizophrenia and with altered cognitive performance." (PMID 35407454, 2022).